JAK1 (Janus kinase 1)
Diseases named in the same sentence as JAK1 in open-access papers (continued):
Sharing a sentence is not in itself a finding about the gene and the disease.
triple-negative breast carcinoma (9 papers, 2016 to 2024). An invasive breast carcinoma which is negative for expression of estrogen receptor (ER), progesterone receptor (PR), and human epidermal growth factor receptor 2 (HER2). "Recent studies of triple-negative breast cancer (TNBC) samples have shown that inhibition of JAK1/2 by ruxolitinib sensitizes cancer cells to paclitaxel, both in-vitro and in-vivo." (PMID 37021933, 2023). "M2 macrophages also promote triple-negative breast cancer progression through the JAK1/STAT1 pathway." (PMID 35269804, 2022). "More recently, a phase II clinical trial evaluating a selective JAK1/2 inhibitor in patients with metastatic triple-negative breast cancer (tumors demonstrating p-STAT3 expression) also demonstrated limited clinical efficacy." (PMID 34445170, 2021). "Ruxolitinib, a JAK1/2 inhibitor is currently in clinical trials for ER+, HER2+ and triple negative breast cancer either as a single therapy or in combination with chemotherapy." (PMID 37005447, 2023). "Currently, ruxolitinib, a JAK1 and JAK2 inhibitor, is being investigated in treatment of primary and metastatic triple-negative breast cancer." (PMID 31060575, 2019).
acute myeloid leukemia (8 papers, 2015 to 2025). Acute myeloid leukemia (AML) is a group of neoplasms arising from precursor cells committed to the myeloid cell-line differentiation. "Another GOF position, JAK1 Val658, is mutated in acute myeloid leukemia (AML); this residue is structurally analogous to JAK2 Val617, which is commonly mutated in polycythemia vera." (PMID 36669486, 2023). "Phase 1 of the phase 1/2 study was conducted to assess INCB052793, a potent JAK1 inhibitor, alone and in combination with standard therapies for patients with MM, acute myeloid leukemia (AML), and myelodysplastic syndrome (MDS)." (PMID 38319731, 2024). "These include Ruxolitinib, a janus kinase 1/2 inhibitor for Primary Myelofibrosis and Polycythemia Vera, Ibrutinib, a bruton kinase inhibitor for B-cell malignancies and most recently Midostaurin, a multi-kinase inhibitor for FMS-like tyrosine kinase 3 (FLT3) mutated acute myeloid leukemia (AML)." (PMID 34238254, 2021). "JAK1 mutations can be found in 10–15% of T-ALL and 1–2% of acute myeloid leukemia (AML) patients." (PMID 34465864, 2022).
influenza (8 papers, 2019 to 2025). An acute viral infection of the respiratory tract, occurring in isolated cases, in epidemics, or in pandemics; it is caused by serologically different strains of viruses (influenzaviruses) designated A, B, and C, has a 3-day incubation period, and usually lasts for 3 to 10 days. "Collectively, overexpression of JAK1 can partly restore cellular response to type I and type II IFNs and display anti influenza activity, suggesting that JAK1 degradation play a critical role in attenuating the antiviral activity of IFNs during IAV infection." (PMID 32532301, 2020). "Previous studies reported that ponatinib can reduce inflammation of obesity and influenza due to its inhibitory effect on the two isoforms of JAK (JAK1 and JAK2)." (PMID 37333458, 2023). "SOCS1 is an ISG induced during influenza infection to inhibit the expression of IFNs and their downstream signaling by inhibiting STAT1 or JAK1, which are required for signaling via this pathway." (PMID 34691044, 2021). "Investigating the JAK1 elimination induced by IAV could help us better understand the pathogenesis of IAV and might provide new therapeutic targets for treating influenza." (PMID 32532301, 2020).
plaque psoriasis (8 papers, 2013 to 2025). "Brepocitinib is an oral selective dual TYK2/JAK1 inhibitor and based on its cytokine inhibition profile is expected to provide therapeutic benefit in the treatment of plaque psoriasis." (PMID 38431923, 2024). "Brepocitinib is an oral JAK1 and TYK inhibitor that is used in moderate and severe plaque psoriasis." (PMID 39201060, 2024). "Oral tofacitinib, is a JAK1 and JAK2 inhibitor and is the most studied oral JAK inhibitor in moderate to severe plaque psoriasis." (PMID 34884596, 2021). "This has led to FDA approval of topical ruxolitinib (marketed as JAK1- and JAK2-selective) and oral preparations of abrocitinib and upadacitinib (both JAK1-selective) for AD, as well as oral deucravacitinib (TYK2-selective) for plaque psoriasis." (PMID 37298195, 2023). "Brepocitinib (PF-06700841) is an oral selective dual TYK2/JAK1 inhibitor targeting signaling of multiple cytokines (IFN, IL-6, IL-12, IL-21, IL-22, and IL-23) and based on its cytokine inhibition profile is expected to provide therapeutic benefit in the treatment of plaque psoriasis." (PMID 38431923, 2024).
renal cell carcinoma (7 papers, 2022 to 2024). "While other ccRCC studies have reported an upregulation of JAK1 in renal cell carcinoma (p < 0.001), specific survival associations with this gene in RCC have not been reported to date." (PMID 38893126, 2024). "Elevated levels of JAK1 protein are beneficial for the formation of immunosuppressive microenvironment in renal cell carcinoma." (PMID 37600786, 2023). "CircSAFB2 in renal cell carcinoma cell-derived EVs functioned as a miR-620 sponge while JAK1 and STAT3 protein levels were tested markedly lower after co-culturing with miR-620 mimics." (PMID 36405712, 2022). "For instance, exosomal circSAFB2 facilitates M2 macrophage polarization in renal cell carcinoma (RCC), leading to increased immune escape and metastasis through miR-620/JAK1/STAT3 axis." (PMID 37365670, 2023). "This correlates with the result that renal cell carcinoma cell-derived EVs induce macrophages express a higher level of JAK1 and STAT3 protein, and miR-620 can prevent the JAK1 and STAT3 expression." (PMID 36405712, 2022).
rosacea (7 papers, 2022 to 2025). A chronic erythematous skin disorder that affects the face. "Transcriptomic analyses have identified STAT3 as a central regulatory node in rosacea skin, and experimental models have confirmed that LL-37 induces upregulation of JAK1, STAT3, and phosphorylated STAT3 in murine lesions." (PMID 40725084, 2025). "Here, we present two cases of patients who received the JAK1 inhibitor upadacitinib and three cases of patients who received the JAK1 inhibitor abrocitinib for the treatment of refractory rosacea." (PMID 39044833, 2024). "We presented two cases of patients who received the JAK1 inhibitor upadacitinib and four cases of patients who received the JAK1 inhibitor abrocitinib for the treatment of refractory rosacea." (PMID 39044833, 2024). "The clinical use of JAK1 inhibitors upadacitinib and abrocitinib in the treatment of refractory rosacea has rarely been explored." (PMID 39044833, 2024). "The JAK1 inhibitors upadacitinib and abrocitinib may be promising medical options for patients with refractory rosacea." (PMID 39044833, 2024).
T-cell acute lymphoblastic leukemia (7 papers, 2016 to 2021). Acute lymphoblastic leukemia of T-cell origin. "JAK1 mutation has been found to involve in the development of AML JAK1 mutations are commonly found in T-cell ALL (18%) and with a lesser frequency in B-cell ALL (B-ALL)." (PMID 29455667, 2018). "JAK1 has been implicated with different kinds of acute leukemia or B-cell lymphoma dependent on mutated sites, JAK2 mutation was usually associated with thrombocytosis, myelofibrosis, leukemia, and lymphoma and increased JAK3 signaling can result in T-cell acute lymphocytic leukemia." (PMID 30564118, 2018). "In contrast, increased JAK1 and JAK3 signaling can lead to T-cell acute lymphocytic leukemia in mice." (PMID 30564118, 2018).
type 1 diabetes (7 papers, 2022 to 2025). "We found that MAPK1, but not RELA, was significantly reduced in the α cells of donors with type 1 diabetes (vs. control and autoantibody-positive donors), whereas JAK1 was expressed at insignificant levels within the islets in all groups." (PMID 37558746, 2023). "A case report showed that JAK1/JAK2 inhibitor ruxolitinib normalized blood-glucose levels and discontinued exogenous insulin in a patient with type 1 diabetes caused by STAT1 gain-of-function." (PMID 35242127, 2022). "DE genes in the PPI networks were also highly connected to type 1 diabetes drug–gene targets, particularly JAK2 and JAK1." (PMID 41306972, 2025). "The baricitinib in new onset type 1 diabetes (BANDIT) trial, will investigate whether the JAK1/JAK2 inhibitor baricitinib, currently used in the treatment of rheumatoid arthritis and alopecia, can facilitate beta-cell survival in individuals with recent-onset (<100 days) T1D." (PMID 37867531, 2023).
fibrosarcoma (6 papers, 2013 to 2021). A malignant mesenchymal fibroblastic neoplasm affecting the soft tissue and bone. "Inactivation of JAK1/2 in fibrosarcoma cells leads to loss of invasion in vitro and metastasis in vivo, and in zebrafish these cells show limited spread throughout the zebrafish body compared with the highly metastatic parental cells." (PMID 24089705, 2013). "JAK1 and JAK2, for example, have been implicated in promoting invasion and metastasis in certain cell types such as 2C4 human fibrosarcoma cells, which are highly invasive." (PMID 24089705, 2013). "Hence, as in other clinical trials when using for example mitogen‐activated protein kinase kinase 1 or rapidly accelerated fibrosarcoma inhibitors, it would be important for JAK1/2 targeting clinical trials to stratify for the K‐RAS mutational status." (PMID 31407334, 2019). "In fibrosarcoma-derived cells, IL-6 signaling depends on the presence of Jak1." (PMID 28708884, 2017).
inflammatory skin disease (6 papers, 2013 to 2025). Inflammatory skin disorders covers a broad category that includes many conditions ranging in severity, from mild itching to grave medical health complications These disorders are common in people of all ages and races. "The emerging consensus supports the use of selective JAK1 inhibition, as it offers a favorable balance between efficacy and safety in the treatment of inflammatory skin diseases." (PMID 40485866, 2025). "This pilot study creates opportunities to evaluate the modulation of JAK1 in applicable rat models of autoimmune and inflammatory skin diseases." (PMID 37925520, 2023). "Suppression of pSTAT3 following topical application of JAK-1/2 inhibitor in cutaneous inflammation has been reported, encouraging hopes that selective JAK inhibitors may play a role in treating inflammatory skin disease as well as JAK2 translocation associated neoplasia." (PMID 23372669, 2013).
Insulin resistance (6 papers, 2008 to 2025). Increased resistance towards insulin, that is, diminished effectiveness of insulin in reducing blood glucose levels. "In PCOS studies, troxerutin troxerutin has been shown to attenuate dihydrotestosterone-induced insulin resistance in rats by inhibiting IL-22/JAK1/STAT3 signaling activation." (PMID 41573199, 2025). "JAK1 mediates cytokine-driven inflammation and contributes to insulin resistance in adipose tissue, while RPS3 links translational control with NF-κB activation, promoting oxidative stress in β-cells." (PMID 40909129, 2025). "Given the critical role of insulin resistance in these patients it was informative in that molecules immediately down stream of the insulin receptor appeared to be down regulated, such as IRS1, CD36 and JAK1/2 (a tyrosine kinase associated with cytokine and metabolic signalling)." (PMID 18997871, 2008). "Hub genes such as GNB1, JAK1, and RPS3 dominated the T2DM network layer, suggesting critical roles in inflammatory signaling, insulin resistance, and translational control under metabolic stress." (PMID 40909129, 2025).
osteosarcoma (6 papers, 2021 to 2025). A usually aggressive malignant bone-forming mesenchymal neoplasm, predominantly affecting adolescents and young adults. "CLDN10 is highly expressed in osteosarcoma cells compared with fetal osteoblast cells, and CLDN10 overexpression in osteosarcoma cells enhances the JAK1/STAT1 signaling pathway to significantly promote proliferation and motility." (PMID 36620607, 2022). "Furthermore, EMT inactivation inhibited proliferation, migration, invasion, and in osteosarcoma by targeting zinc finger E-box-binding protein 1 (ZEB1) through inactivation of c-Jun N-terminal kinase (JNK) and JAK1/signal transducer and activator of transcription 3 (STAT3) pathways." (PMID 33472642, 2021).
pulmonary fibrosis (6 papers, 2018 to 2023). Chronic progressive interstitial lung disorder characterized by the replacement of the lung tissue by connective tissue, leading to progressive dyspnea, respiratory failure, or right heart failure. "In this study, we established in vivo and in vitro models to analyze the effect of JAK1/2 inhibitor baricitinib in pulmonary fibrosis." (PMID 36903446, 2023). "In summary, our results show that JAK1/2 inhibitor baricitinib had the efficacy on restraining pulmonary fibrosis progression by suppressing TGF-β1-induced fibroblasts activation and epithelial injury." (PMID 36903446, 2023). "In a mouse model of bleomycin-induced pulmonary fibrosis, JAK1 has been overexpressed and its active form was increased in the lungs." (PMID 36297334, 2022). "In the current study, the expression level of JAK1, STAT3 and ADAM17 decreased in FFK treatment group compared to BLM treatment group, thus indicating the possible pathways implicated in lung fibrosis as targets of therapeutic attempts." (PMID 30092799, 2018). "This study examined the role of JAK1/2 inhibitor baricitinib in pulmonary fibrosis." (PMID 36903446, 2023). "Our results show that JAK1/2 and STAT3 were activated in animal and cell models of pulmonary fibrosis and that baricitinib has therapeutic effects on pulmonary fibrosis by selectively inhibiting JAK1/2, including reducing the collagen deposition and improving pulmonary function in BLM-injured mice." (PMID 36903446, 2023). "Collectively, this study suggests that fibroblast VDR upregulation may be a self-protective response to limit fibroblast proliferation and activation during pulmonary fibrosis by suppressing the JAK1/STAT3/ER stress pathway." (PMID 37627629, 2023). "FOFB has a therapeutic effect on inflammation-mediated idiopathic pulmonary fibrosis, and its mechanism may be to inhibit the expression of p-JAK1 and p-STAT1 inflammatory proteins by upregulating the expression of SOCS3." (PMID 32908556, 2020). "In conclusion, baricitinib, a JAK1/2 inhibitor, impedes myofibroblast activation and epithelial injury via targeting the TGF-β1 signaling pathway and reduces BLM-induced pulmonary fibrosis in mice." (PMID 36903446, 2023). "The study aimed to explore the effect of total flavonoids of Oxytropis falcata Bunge (FOFB) on the expression of p-JAK1/p-STAT1 and SOCS3 proteins in idiopathic pulmonary fibrosis (IPF)." (PMID 32908556, 2020). "qRT-PCR and Western blot analysis showed that JAK1, STAT3 and ADAM17 levels increased in the pulmonary fibrosis model in vivo, whereas FFK remarkably decreased JAK1, STAT3 and ADAM17 expression." (PMID 30092799, 2018). "Previous studies have reported the pro-fibrotic activity of JAK2 and STAT3 in pulmonary fibrosis, but the involvement of JAK1 has not been well studied." (PMID 36903446, 2023).
sarcoidosis (6 papers, 2022 to 2026). Sarcoidosis is a multisystemic disorder of unknown cause characterized by the formation of immune granulomas in involved organs. "Currently, the reports of JAKi in treating sarcoidosis have primarily used tofacitinib orally, a JAK1/JAK3 inhibitor, or ruxolitinib, a JAK1/JAK2 inhibitor, topically." (PMID 39345281, 2024). "Tofacitinib appears to provide an effective means of suppressing IFN-γ, which signals via JAK1/2, in sarcoidosis." (PMID 35668129, 2022). "Tofacitinib is a JAK1/3 inhibitor that has shown efficacy in refractory sarcoidosis." (PMID 41446689, 2026). "Ruxolitinib, a JAK1/2 inhibitor, has demonstrated efficacy in refractory sarcoidosis." (PMID 41446689, 2026). "However, the potential effectiveness of new selective JAK1 inhibitors, such as upadacitinib, in treating sarcoidosis may represent a promising direction for future studies." (PMID 39904950, 2025). "We also found that the activity of other cytokines including GM-CSF (JAK2), IL-15 (JAK1/3), IL-6 (JAK1/2), IL-12 (JAK2/TYK2) and TNF (JAK-independent) are also evident in sarcoidosis." (PMID 35668129, 2022). "The majority of these SNPs were validated in AAs, with rs7549445, the top ranked SNP by p value, related to JAK1 gene, a Janus kinase, key component of the interleukin-6 (IL-6)/JAK1/STAT3 immune and inflammation response, supporting the importance of the JAK-STAT pathway in sarcoidosis." (PMID 38390497, 2023). "No previous cases of sarcoidosis treated with UPA, a selective JAK1 inhibitor, have been reported." (PMID 39345281, 2024).
T-cell prolymphocytic leukemia (6 papers, 2015 to 2024). A slow-growing type of leukemia (blood cancer) in which too many lymphocytes are found in the bone marrow and/or blood. "For example, in addition to the pathognomonic alterations of the TCL1 gene, T-cell prolymphocytic leukemia (T-PLL) frequently displays point mutations of JAK1 (6.3% of cases), JAK3 (36.4%), and STAT5B (18.8%)." (PMID 38638855, 2024). "A recent publication using integrated genomic sequencing shows gain-of-function mutations in JAK1, JAK3 and STAT5B in T cell prolymphocytic leukaemia (T-PLL), supporting the importance of JAK kinases for T cell lymphoma growth." (PMID 25820993, 2015).
type 2 diabetes (6 papers, 2015 to 2025). "The observed reduction in the expression of JAK1 supports the potential of CR to attenuate local inflammation in low grade inflammatory diseases (i.e., metabolic syndrome, obesity, and type 2 diabetes) that could predispose to cancer." (PMID 31450563, 2019). "The results of phase II clinical trials on baricitinib (another JAK1/JAK2 inhibitor) indicated reduced urinary ACR by 40% over 24 weeks in patients with Type 2 diabetes and DKD." (PMID 34202668, 2021).
allergic asthma (5 papers, 2020 to 2025). A asthma with a basis in a pathological type I hypersensitivity reaction. "Our RT-qPCR results showed that Lif, Jak1, and Stat3 transcription increased in lung tissues from mice with allergic asthma and decreased after emu-miR-10a-5p intervention." (PMID 40496853, 2025). "Cyanidin-3-O-glucoside (C3G) prevented the progression of allergic asthma in a murine model through STAT6/GATA3 signaling suppression, whereas another cyanidin, procyanidin A2, reduced the expression of CCL26 in human keratinocytes via JAK1/STAT6 signaling." (PMID 35566102, 2022).
anaplastic large cell lymphoma (5 papers, 2019 to 2022). Anaplastic large cell lymphoma (ALCL) is a rare and aggressive peripheral T-cell non-Hodgkin lymphoma, belonging to the group of CD30-positive lymphoproliferative disorders, which affects lymph nodes and extranodal sites. "While STAT3 activation is induced by ALK fusion proteins in ALK-positive ALCL, it is induced by somatic mutations of STAT3 and JAK1 in 20% of ALK-negative anaplastic large cell lymphomas and 5% of primary cutaneous ALCL, whereas mutations in these genes have not been reported for CD30+ PTCL." (PMID 35330161, 2022). "In anaplastic large cell lymphoma (ALCL), JAK1 and STAT3 are activated by high levels of cytokines, including IL-6." (PMID 31861597, 2019). "Activating mutations in JAK1 are found in CTCL, natural killer cell lymphoma (NKCL) and large granulocytic leukemia (LGL), as well as in 20% of ALK-negative anaplastic large cell lymphoma (ALCL), and treatment with ruxolitinib reduced tumor growth in an ALK-negative ALCL PDX model in vivo." (PMID 34066732, 2021).